MIR597 (microRNA 597)
Synonyms: hsa-mir-597; MIRN597; mir-597
Gene: MicroRNA gene on chromosome 8 (9,741,672 to 9,741,768, forward strand). Ensembl gene ENSG00000207701.
Gene Ontology:
Biological process: miRNA-mediated post-transcriptional gene silencing
Homologues: Orthologues: chimpanzee ptr-mir-597 (100% identical), macaque mml-mir-597 (93% identical).
Diseases named in the same sentence as MIR597 in open-access papers:
MIR597 is named in the same sentence as 2 diseases in open-access papers, as found by Europe PMC text mining. Sharing a sentence is not in itself a finding about the gene and the disease. The quoted sentences say what the papers report.
cancer (1 paper, 2023). A tumor composed of atypical neoplastic, often pleomorphic cells that invade other tissues. "In estrogen receptor-positive cancer with mass lesion type, CCL3L1 (21-fold), SNHG12 (11-fold), and MIR206 (sevenfold) were upregulated, and MIR597 (265-fold), MIR126 (12-fold), and SOX17 (fivefold) were downregulated." (PMID 37391754, 2023).
MIR597 also shares sentences with these, for which no sentence is quoted: tumour (1 paper).